IL6 (interleukin 6)
Diseases named in the same sentence as IL6 in open-access papers (continued):
Sharing a sentence is not in itself a finding about the gene and the disease.
infection (continued). "Whilst levels of IL-6 in the lungs of mice were significantly increased across all time points tested, concurrent with the bacterial burden in the lungs, the highest levels of IL-6 were detectable at 7 days post-infection." (PMID 37624013, 2023). "Further investigation demonstrated that apoE23 reduced plasma TNF-α, IL-6, and LPS levels; decreased bacterial load in spleen tissue; and attenuated infection-induced lung, liver, and small intestine injuries in septic mice." (PMID 37533741, 2023). "In line with the present study and although a smaller set of analytes was investigated (59 vs. 27), IL-8, IP-10, and IL-6 levels were again increased following infection." (PMID 36731656, 2023). "Following infection, the proinflammatory cytokines IL-1β, TNFα, and IL-6 were upregulated in the olfactory bulb and hippocampus at DPI-4." (PMID 38006064, 2023). "While Il1β, Il6 and Tnfα show a significantly altered gene expression after infection for both, DMSO and DEVD-fmk treated BV2." (PMID 36906641, 2023). "Higher levels of IL-6 were observed between four to 14 days post-infection in the pre-treated group compared to the untreated group." (PMID 37125086, 2023). "It is therefore imperative to investigate the potential of urinary IL-6 and IL-10 in morbidity monitoring under low infection endemicity setting." (PMID 37018184, 2023). "Cytokine assay confirmed that as the infection time prolonged, the levels of inflammatory cytokines (especially IL-6 and: IL-1β) decreased, while anti-inflammatory cytokines (especially IL-4) increased." (PMID 38076459, 2023). "Infection of BV2 cells with JEV resulted in significant higher expression of IL-6, TNF-α, MCP-1 and IL-1β as compared to un-infected cells." (PMID 36707891, 2023). "In agreement with this, we found that TLR2 signaling was required for increased release of IL-6 in response to infection with the Schu S4 ∆tolC mutant." (PMID 37404047, 2023). "The binary logistic regression model presented a significant effect of serum IL-6 concentration in forecasting an increased duration of infection." (PMID 36679958, 2023). "We found that IL-6 and IL1β in the infection group were much higher than those in the control group by ∼7 fold and ∼17 fold, respectively." (PMID 40303727, 2023). "TXB2 is a potent activator of platelet aggregation whose effectiveness is enhanced by IL6, which is extremely elevated in patients who have died of the infection." (PMID 37686388, 2023). "Compared with the asymptomatic group, patients with symptoms were younger, and exhibited higher interleukin-6 levels and lower post-infection phosphate levels (p < .05)." (PMID 37501590, 2023). "CRP transcription and synthesis is primarily induced by IL-6 and results in the activation of the classical complement pathways and the recruitment of phagocytic cells to the site of infection." (PMID 37019645, 2023). "Studies with other arthritogenic alphavirus such as CHIKV and RRV have shown osteoblasts to be susceptible to infection, leading to secretion of MCP-1, IL-1, and IL-6." (PMID 37983245, 2023). "Cytokines (e.g., TNF, IL-1β, IL-6, interleukin-17 (IL-17)) from macrophages, mast cells, and other immune cells interact with sensory neurons through these cytokine receptors during infection/inflammation, allergy, and tissue damage/injuries." (PMID 37767094, 2023). "In order to functionally validate ZFP36L1’s role in regulating IL-6 transcript stability upon infection, we knocked down ZFP36L1 expression in primary B cells with a specific siRNA prior to EBV infection." (PMID 37830871, 2023). "Systemic inflammatory responses to infection are responsible for triggering the activation of microglial cells by excessive production of proinflammatory cytokines, including interleukins (IL-6, IL-2, IL-12, and IL-15) and tumour necrosis factor alpha (TNF-α)." (PMID 37261613, 2023).
infection (continued). "The mechanism demonstrates that the protective effect of IL-6 against oxidative stress plays a crucial role in regulating the pro-oxidative environment in the early stages of infection." (PMID 37818368, 2023). "The naïve infection control group showed the highest levels of IFN-γ, TNF-α, IL-6, and IL-1β cytokines in lung samples at 6 days after infection." (PMID 37515025, 2023). "Cytokine IL-6 initiates the CRS in the MAPK/NF-κB-IL-6 or JAK-STAT pathway, and as an infection trigger, IL-6 has been associated with the symptom progression in this disease." (PMID 37033914, 2023). "Bacterial toxins are crucial in the induction of the synthesis of this protein, which is also stimulated by high levels of tumor necrosis factor (TNF-α) and interleukin-6 (IL-6), produced in response to infection." (PMID 37762882, 2023). "The release of four key mediators (MCP-1, TNF, IL-10, and IL-6) into the supernatant of cell cultures was measured before and after infection with BCG or stimulation with MDP." (PMID 36972292, 2023). "Treatment of mice with DSS and infection with parasites resulted in increased levels of IL-6, TNF-α, and IL-10 in serum; IL-1β and IL-6 in the colon; and IL-6 in the small intestine." (PMID 36836678, 2023). "qRT-PCR analysis showed that in vivo infection of E. tarda significantly upregulated the expression of IL-6 and IL-8 in flounder kidney and spleen." (PMID 37239318, 2023). "In our study, only measures of IL-6 and CrP were available for analyses as these were part of the routine work-up at expected inflammation/infection." (PMID 37049507, 2023). "HCoV-OC43 induced little IFN-β and IL-6 production over the whole time course, whereas HCoV-229E suppressed IFN-β production throughout the course of infection but IL-6 expression gradually increased over time." (PMID 36507221, 2023). "In the nasal turbinates, Wuhan/ΔORF7ab infection also induced a higher expression of Mx2, but also Il-6, Cxcl10, Tnf-α and Il-10." (PMID 37495586, 2023). "An increase in the levels of IL-6 not only occurs in the acute infection period but is also one of the most critical factors that contributes to post-COVID-19 syndrome after a time window of four weeks post infection." (PMID 37095536, 2023). "There was an increase in IL-6, IL-17, and melatonin in the group of elderly individuals with infection." (PMID 37239991, 2023). "IL-6 stimulates acute phase macrophage responses, enhances B cell growth and antagonizes T cell responses to infection." (PMID 37923927, 2023). "We found that infection with Salmonella excessively upregulated ileal, colonic, and plasma IL-6 and IL-12/23/p40 levels within the acute phase of the immune response." (PMID 36768650, 2023). "With exacerbated oxidative stress and cytokine storm, increased levels of interleukin-6 (IL-6) and decreased levels of interferon-β (IFN-β) are thought to contribute to worsening infection and are also associated with decreased levels of GSH." (PMID 37005767, 2023). "Infection also elicits a relatively high number of eosinophils (personal observations) which can secrete IL-10 and IL-6 cytokines." (PMID 36839863, 2023). "More importantly, in vivo analysis showed that at the peak of IL-6 transgenic parasite growth in the liver, namely at 48h post-infection, IL-6 mRNA transcripts were detected at the same time, suggesting an in vivo secretion of IL-6." (PMID 37143657, 2023). "In contrast, IL-6 is usually rapidly synthesized in response to infection by pathogens and tissue damage." (PMID 37513733, 2023). "The pro-inflammatory markers profile (CRP, IL1, IL6 and TNFα) was generally abnormal in the infection group in week 0 and those values seemed to improve throughout the weeks." (PMID 37762523, 2023). "As an alternative strategy, we generated a liver stage-arresting IL-6 transgenic Plasmodium parasites which not only blocks blood stage infection but also conferred a long-lasting protection against virulent challenge with WT parasites." (PMID 37143657, 2023).
infection (continued). "The clinical score data revealed that all IL-6−/− mice and some WT mice developed severe neurological symptoms after infection." (PMID 38053527, 2023). "As can be shown, following CsA infection in mouse lung tissue, IL-1β and IL-6 mRNA gene expression was dramatically increased, while IL-10 mRNA gene expression was markedly decreased." (PMID 38259457, 2023). "Prior to HIV infection the paired pre-infection biomarker levels demonstrated intraparticipant stability, except for significant variability in IP-10, IL-6 and sCD163 (N=50)." (PMID 37461626, 2023). "In this model, we demonstrated that the intra-hepatocyte parasite development was impaired via an IL-6-dependent mechanism and the abortive infection resulted in a long-lasting immunity in Mdr2−/− mice against infectious SPZ." (PMID 37143657, 2023). "IL-6 concentrations spike very early in the course of infection or inflammation, followed by an increase in hepcidin, then a rise in CRP and finally the release of AGP37." (PMID 37365154, 2023). "During infection with hepatotropic viruses, the long-term production of Il-6, IL-8, and TNF-α leads to the generation of free radicals." (PMID 37507865, 2023). "Increased expression of TNF-α, IL-1β, and IL-6 was seen predominantly with DENV2 infection and at higher levels with Mon601 compared with DENV1 and DENV2 field isolates." (PMID 37515098, 2023). "The prognostic quality of serum IL-6 concentration regarding the clinical consequence of infection was calculated in a ROC analysis." (PMID 36679958, 2023). "Inflammatory cytokines, TNF, interleukin 6 and 1 β (IL-6, and IL-1β) levels increase over the course of infection in specific tissues where pathogen-specific T cells are present." (PMID 36911729, 2023). "Twenty-four h after infection IL-10, LIF, M-CSF, IL-6, and IL-27 upregulation with the same mAbs was associated with protection in mice." (PMID 37289480, 2023). "For CRP, PCT, and IL-6 provide results in an hour, but the time from initiation of infection to biomarker detection takes about 1–3 h." (PMID 37932249, 2023). "Other studies examining SARS-CoV-2-exposed bronchial cells have also showed that IL-6 was produced at 72 h after infection, consistent with the response we observed in non-AUD cells." (PMID 37786945, 2023). "We found that both POPG and PI inhibited IL6 gene expression (by 50% and 60%, respectively) and protein production (by 57% and 80%, respectively) after RV-A16 infection (shown as % of RV16, RV16 + POPG: 42.5 ± 8.5, RV16 + PI: 20.4 ± 5.9)." (PMID 36992456, 2023). "To test if EhaF can inhibit epithelial cell innate immune responses, we infected Caco2 cells with wild-type EHEC or ΔEhaF and measured IL-8 and IL-6 levels at 24 h post-infection (p.i.)." (PMID 37041208, 2023). "Levels of IFN-γ, TNF-α, IL-6, and IL-10, which are important for the activation of protective immunity, were significantly increased at the early stage of ΔPbMAP1 infection." (PMID 37563696, 2023). "Interleukin 6 (IL-6) is a cytokine that is involved not only in immune responses to inflammation and infection, but also regulates metabolic, regenerative, and neuronal processes." (PMID 37687297, 2023). "M2 macrophages can be induced by interleukin-6 (IL-6) and play an important role in the elimination of infection and repair of tissue damage." (PMID 37159798, 2023). "Second, in this work, we utilized IL-6 level and viral load to represent infection severity and classify immune responses." (PMID 37656752, 2023). "Our results show a critical role of early acute TNFα production within the first hour after the infection before the reported IL6 and IL10 production in both experimental and clinical studies." (PMID 37520526, 2023). "The results of the ROC analysis and the binary logistic regression revealed that the estimation of IL-6 at the onset of infection was an appreciated tool for recognizing cattle developing a prolonged duration of the disease." (PMID 36679958, 2023).
infection (continued). "TNF-α, IL-6, and IL-1β are primary cytokines generated by activated macrophages during initial inflammatory responses of host defense and infection, consistent with previous reports." (PMID 38015971, 2023). "In response to infection, neutrophils are recruited to the lungs depending on the cytokine signaling pathways of IL-6, nuclear factor kappa B, and tumor necrosis factor." (PMID 36910136, 2023). "Next, we evaluated the release of IL-8 and IL-6 upon infection of GES-1 and AGS cells with the two strains." (PMID 37894827, 2023). "Both CRP and IL-6 are established biomarkers for postnatal infection, but their relative utility and specificity are debated." (PMID 37606448, 2023). "The results indicate that LGP2 knockdown (siRNA si-2 shows the best inhibition effect was chosen) significantly increases the mRNA levels of IFNβ, ISG56, Mx1 and IL6 at multiple post infection time points, and IκBα and CXCL10 at 24 hpi." (PMID 37656756, 2023). "At 3 d post-infection, all the cytokine levels of IL-6, MCP-1, TNF-α, and IFN-γ in ΔTgLOXL1-infected mice were lower compared to the cytokine level in parental-infected mice." (PMID 37646522, 2023). "Interleukin-1 (IL-1) and interleukin-6 (IL-6) are pro-inflammatory cytokines that are released in response to tissue damage, inflammation, and infection." (PMID 37408225, 2023). "Similar to our findings, there were mid-infection increases in circulating cytokines, IL-6, IL-12 and IFNγ with peak levels at day 14 post- inoculation for IL-12, day 21 for IFNγ and day 28 for IL-6." (PMID 36893126, 2023). "Intriguingly, in TLR2−/−/old mice, the most severely sick group with the highest weight loss and bacterial persistence in the kidneys, displayed a weak IL-6 response to infection, suggesting that advanced age has a great impact on IL-6 production." (PMID 36808423, 2023). "In the initial stage of infection, groups C and D had lower levels of the proinflammatory cytokines IL-6, TNF-α, and IFN-γ and higher levels of anti-inflammatory cytokine IL-10 than the other groups." (PMID 37051240, 2023). "In response to these atypical findings, we surmised that the Il6 and Tnf levels differed during the early and late stages of infection, respectively." (PMID 37854611, 2023). "Surprisingly, we found that IL-4, IL-5, IL-6, IL-10, and IL-13 levels reached peaks after 30 days of infection and then decreased in a time-dependent manner." (PMID 37691941, 2023). "The previous colonization of piglets with BB12 prevented a significant increase in IL-6 and IL-12/23p40 intestinal and plasma levels after infection with Salmonella compared to control GF piglets." (PMID 36768650, 2023). "At 48 h after infection, IL-10 expression was increased significantly, whereas transcription of IL-6 and IL-12 was decreased significantly, and the presentation of activated caspase-3 protein fell." (PMID 37841250, 2023). "A study in highly endemic area of coastal Kenya assessed different cytokines and suggested that interleukin (IL)-6 and -10 in urine of children infected with S. haematobium are correlated with morbidityand infection intensities." (PMID 37018184, 2023). "Third, our study did not compare the difference in diagnostic efficacy with other indicators, such as IL-6, SAA, FER, and HBP, that also indicate the severity of the infection." (PMID 37180431, 2023). "IL-6 is a proinflammatory cytokine secreted upon infection by various cells such as T lymphocytes, B lymphocytes, monocytes and endothelial cells." (PMID 37600000, 2023). "Overall we noticed a drastic increase in IL6 level at later time points post infection compared to initial time points." (PMID 36707891, 2023). "IL-6 is considered one of the most important cytokines during an infection, along with IL-1 and TNF-α." (PMID 36707891, 2023).
infection (continued). "C-reactive protein (CRP) is γ-globulin produced by the liver and classified as an acute phase reactant, which means that it rises in response to general inflammation, infection, or tissue injury following IL-6 secretion by macrophages." (PMID 37542317, 2023). "Interleukin 6 (IL-6) is a pleiotropic protein with a range of activities, including neutrophil differentiation during infection and protection against septic shock, and tumorigenic and tumorostatic activities." (PMID 37854742, 2023). "IL-6 is a cytokine expressed at the earliest stage of tissue injury and infection that induces the synthesis of C-reactive protein (CRP) and fibrinogen in the acute phase response." (PMID 38813035, 2023). "Higher levels of IL-1β and IL-6 were detected in cultures sensitized prior to infection compared to unstimulated infected cells." (PMID 37841240, 2023). "IL-6 is involved in the acute hepatic inflammation phase and is produced instantly and transiently in infection response." (PMID 38131990, 2023). "Epithelial cells are known to produce various proinflammatory cytokines and chemokines that include CXCL1, IL-6, IL-8, as well as GM-CSF following infection with C. trachomatis." (PMID 36870960, 2023). "Particularly, a significant difference was observed for TNF‐α, IL‐8, and MCP‐1 four h post‐infection, and of IL‐6, IL‐8, and MCP‐1 24 h post‐infection in U937 macrophages and hGFBs, respectively." (PMID 35964247, 2023). "In mammal species, immune cell receptors trigger the arrival of lymphocytes at the site of infection together with the interleukin-derived immune response (IL-1 α, β, and IL-6)." (PMID 37235418, 2023). "We performed qRT-PCR to measure the expression levels of IFN-α and IFN-β in brain homogenates collected from WT and IL-6−/− mice at 3-, 6-, and 8 days after infection." (PMID 38053527, 2023). "Here we showed that expression of TNF-α was inhibited at all time points while IL-6 was decreased at 48 h post-infection only compared to the control." (PMID 37280772, 2023). "IL-6 is notorious for a proinflammatory cytokine that stimulates hsCRP production during acute inflammation and infection." (PMID 36671520, 2023). "Median IL-6 levels in the infection group and the asymptomatic group were 350 (252.5-400) pg/ml and 48.50 (10.58-62.88) pg/ml, respectively, p<0.001." (PMID 36895535, 2023). "Our data shows that, as compared to ancestral Wuhan-Hu-1 strain, BA.5 infection in hACE2.Tg mice shows an overall decrease in the mRNA expression of IL-4, IL-6, IL-17A, and IL-33." (PMID 37704701, 2023). "GO analysis of upregulated infection genes at three weeks indicated immune-related processes, including regulation of the cytokines IL6, IL1, IL12, IL10, IL8 and TNF, as well as macrophage activation, and responses to wounding." (PMID 37200402, 2023). "The key result was that the cattle developing an extended duration of infection showed considerably elevated IL-6 concentration at the initial symptoms." (PMID 36679958, 2023). "Our study revealed top 8 cytokines (IL-17, IL-1α, IL-2, IL-10, IL-5, IFN-γ, TNF-α and IL-6) and their biomarker abilities to discriminate different stages of infection." (PMID 36646786, 2023). "For this, different groups of mice were infected with IL-6 Tg-PbANKA/LISP2 SPZ using either 104 SPZ (group 1) or 5 x 104 SPZ (group 2) followed by a challenge with 104 WT PbANKA SPZ at day 30 post-infection with IL-6 Tg parasites." (PMID 37143657, 2023). "Pro-inflammatory IL-6 was significantly increased in severe infection (p = 0.009) while TNFα was decreased (p = 0.016) compared to healthy controls." (PMID 37598150, 2023). "Like IL-6 levels, we noticed an Upregulated expression of IL-17 level with increasing time points post infection." (PMID 36707891, 2023). "IL-6 is known to respond with broad-ranging effects to infection and tissue injury, and contribute to the host’s defence." (PMID 37761018, 2023).